CCL3 (C-C motif chemokine ligand 3)
Diseases named in the same sentence as CCL3 in open-access papers (continued):
Sharing a sentence is not in itself a finding about the gene and the disease.
cutaneous leishmaniasis (2 papers, 2013 to 2024). Leishmaniasis affecting the skin. "To determine if CCR5 was associated with more severe disease in mice, we evaluated Ccl3, Ccl4, and Ccr5 gene expression in lesions from two murine models of severe disease in murine cutaneous leishmaniasis." (PMID 38709823, 2024). "Supporting this idea, in the more chronic and severe diffuse forms of cutaneous leishmaniasis, the former chemokines are expressed in low levels, and there are high amounts of CCL3." (PMID 23533582, 2013). "Conversely, in skin lesions taken from patients with localised (typically self-healing) cutaneous leishmaniasis, CXCL9, CXCL10 and CCL2 are highly expressed, and CCL3 is only present in low levels, this response perhaps being part of an effective immune response." (PMID 23533582, 2013).
demyelinating disease (2 papers, 2023). A broad group of disorders that affect the myelin sheaths that cover the neurons. "CCL3, IFN-γ, and TNF-α are T helper 1 cytokines and they play a pathogenic role in other demyelinating diseases namely MS in which they drive the recruitment and activation of immune cells and elicit toxic or proapoptotic effects on oligodendrocytes." (PMID 37525026, 2023). "Similarly, CCL3 and CCL4 have been shown to contribute to demyelinating disease." (PMID 37496672, 2023).
diffuse cutaneous Leishmaniasis (2 papers, 2012 to 2017). A form of LEISHMANIASIS, CUTANEOUS caused by Leishmania aethiopica in Ethiopia and Kenya, L. pifanoi in Venezuela, L. braziliensis in South America, and L. mexicana in Central America. "In humans, CCL2 expression correlated with self healing cutaneous lesions, whereas CCL3 was associated with lesions of chronic progressive diffuse cutaneous leishmaniasis caused by L. mexicana." (PMID 22679519, 2012).
Hashimoto thyroiditis (2 papers, 2024 to 2025). An autoimmune disorder caused by the production of autoantibodies against thyroid tissue. "Increased expression of chemokines like CCL2 and CCL3 in Hashimoto’s thyroiditis patients suggests their role in inflammatory responses and tissue damage by attracting immune cells to the thyroid gland." (PMID 40837371, 2025).
hemolytic-uremic syndrome (2 papers, 2022). Acute kidney injury associated with microangiopathic hemolytic anemia and thrombocytopenia. "Upregulation of CCL2 and CCL5, and to a lesser extent CCL3, was also shown to mediate the accumulation of macrophages in kidney in a mouse model of the hemolytic-uremic syndrome." (PMID 35203629, 2022).
intrahepatic cholangiocarcinoma (2 papers, 2023 to 2025). A carcinoma that arises from the intrahepatic bile duct epithelium in any site of the intrahepatic biliary tree. "In intrahepatic cholangiocarcinoma (ICC), hepatocyte-secreted CCL3 promotes metastasis via VIRMA-mediated m6A modification, which upregulates SIRT1 and drives tumor progression." (PMID 40034695, 2025).
kidney cancer (2 papers, 2017 to 2022). Primary or metastatic malignant neoplasm involving the kidney. "Studies have revealed that cancer-related fibroblasts are involved in enhancing the migratory properties of the prostate, kidney, and kidney cancer, by secreting several stimulating factors such as IL-6 or CCL3 that activate STAT3." (PMID 36230984, 2022). "However, the expression levels of CCL3 was only significantly increased in the group with kidney cancer." (PMID 28122354, 2017).
malnutrition (2 papers, 2017 to 2022). Inadequate nutrition resulting from poor diet, malabsorption, or abnormal nutrient distribution. "Ccr5, another receptor for Ccl3, was only upregulated due to malnutrition (p < 0.0001)." (PMID 28397794, 2017).
mantle cell lymphoma (2 papers, 2020 to 2025). Mantle cell lymphoma is a rare form of malignant non-Hodgkin lymphoma affecting B lymphocytes in the lymph nodes in a region called the ``mantle zone''. "In mantle cell lymphoma, B cell-derived CCL3 forms a positive feedback loop with M2 macrophages: CCL3 promotes M2 polarization, and M2 macrophages secrete IL-10 to further stimulate CCL3 secretion by MCL cells, accelerating tumor growth." (PMID 41246318, 2025).
memory impairment (2 papers, 2019 to 2025). "In this review, we highlight some studies in which cytokines (e.g., IL-1β, CCL-3) were injected directly into the brain parenchyma, inducing memory impairment." (PMID 40352932, 2025).
mesothelioma (2 papers, 2019 to 2024). A usually malignant and aggressive neoplasm of the mesothelium which is often associated with exposure to asbestos. "Interestingly, chemokines involved in monocyte/macrophage recruitment and mobilization such as CCL2, CCL3, CCL4, and CCL7 were downregulated in the mesothelioma cell line compared to two other tested cell lines." (PMID 39768223, 2024).
metastasis (2 papers, 2020 to 2021). The spread or migration of cancer cells from one part of the body (where they first appeared) to another. "As T cells may be responding to CCL3 during bone metastasis, we analyzed T cell subpopulations with FACS." (PMID 32221289, 2020). "In addition, we found that CCL3 was highly expressed in ccRCC patients with axillary regional lymph node metastasis compared with those without lymphatic metastasis." (PMID 34732692, 2021).
microcephaly (2 papers, 2018 to 2021). A congenital or acquired developmental disorder in which the circumference of the head is smaller than normal for the person's age and sex. "Unsupervised hierarchical cluster analysis demonstrated that ZIKV-exposed individuals with microcephaly exhibited a tendency of increased levels of pro-inflammatory mediators in CSF, as IL-1β, IL-12p70, IL-15, IL-17A, IFN-γ, and MIP-1α (CCL3) compared to controls." (PMID 33875756, 2021).
muscular dystrophy (2 papers, 2009 to 2020). Muscular dystrophy (MD) refers to a group of more than 30 genetic diseases characterized by progressive weakness and degeneration of the skeletal muscles that control movement. "In this regard, we have recently reported a marked upregulation of CCR1 and two of its major ligands, RANTES (CCL5) and MIP-1α (CCL3), in the diaphragms of muscular dystrophy (mdx) mice and demonstrated a relationship with the degree of muscle infiltration by mononuclear inflammatory cells." (PMID 19421418, 2009). "Our data showing elevated levels of several CC-motif-containing chemokines extend prior studies showing increased expression CCL2, CCL3, and CCL4 in muscle biopsies obtained from animal models and human patients suffering from muscular dystrophy or inflammatory myopathies." (PMID 33138863, 2020).
Myalgia (2 papers, 2025 to 2026). "CRP was significantly higher in patients with these symptoms, while chemokines CCL2 (MCP-1), CCL3 (MIP-1α) and CXCL8 (IL-8) were higher in patients with rigors and myalgia." (PMID 41027884, 2025).
myeloproliferative neoplasm (2 papers, 2017 to 2021). A clonal hematopoietic stem cell disorder, characterized by proliferation in the bone marrow of one or more of the myeloid (i.e., granulocytic, erythroid, megakaryocytic, and mast cell) lineages. "CCL3 may cause myeloproliferative neoplasm (MPN) in a different manner." (PMID 28829353, 2017).
necrotizing enterocolitis (2 papers, 2023 to 2024). Necrotizing enterocolitis (NEC) is a devastating disease that affects mostly the intestine of premature infants. "CCL3 was elevated in preterm infants with necrotizing enterocolitis and in a mouse model." (PMID 37496672, 2023). "CCL3 promotes apoptosis by activating the ERK1/2 and NF-κB pathways in necrotizing enterocolitis (NEC)." (PMID 38730482, 2024).
overnutrition (2 papers, 2011 to 2022). An imbalanced nutritional status resulting from excessive intake of nutrients. "Overnutrition increases the levels of inflammatory molecules, such as TNF, IL-6, CCL2 and CCL3, in adipocytes, which activate resident macrophages, leading to the recruitment of more immune cells." (PMID 35112705, 2022).
pneumococcal infection (2 papers, 2015 to 2020). Infections with bacteria of the species streptococcus pneumoniae. "Pneumococcal infection as well increased the mRNA expression levels of pro-inflammatory cytokines and chemokines, including Tnf-α, Il-6, Ccl3, and Cxcl10, which were equally reduced after treatment with Ac2-26." (PMID 33121515, 2020). "Furthermore, inhibiting IL-10 resulted in an increase in CCL3 and CCL5, two of the chemokines that were increased in aged mice following pneumococcal infection." (PMID 25595646, 2015).
pneumococcal meningitis (2 papers, 2013 to 2016). An acute purulent infection of the meninges and subarachnoid space caused by Streptococcus pneumoniae, most prevalent in children and adults over the age of 60. "The intracisternal inoculation of recombinant CCL3 and CCL4 induced BBB disruption, CSF leukocytosis, and cerebral edema in a rabbit model of pneumococcal meningitis." (PMID 23997430, 2013). "In vitro, antibodies against CCL2, CCL3, and CCL4 inhibited monocyte chemotactic properties of CSF from patients with pneumococcal meningitis." (PMID 23997430, 2013). "Patients with pneumococcal meningitis show high levels of pro-inflammatory cytokines such as TNF-α, IL-1β, IFN-γ, IL-2, IL-6 and IL-12, anti-inflammatory cytokines (IL-10 and TGF-β) and chemokines such as CXCL8 (IL-8) CCL3 (MIP-1a) and CCL2 (MCP-1) in their CSF." (PMID 26744349, 2016).
Pruritus (2 papers, 2022 to 2023). Pruritus is an itch or a sensation that makes a person want to scratch. "Among the studied chemokines (C-C Motif Chemokine Ligand (CCL) 2/MCP-1, CCL3/MIP-1α, CCL4/MIP-1β, CCL5/RANTES, CXCL8/IL-8, CCL17/TARC, CCL18/PARC, CCL22/MDC), only CCL17/TARC showed a positive correlation with pruritus intensity." (PMID 37834183, 2023). "The aim of the study was to analyse serum concentrations of CCL2/MCP-1, CCL3/MIP-1α, CCL4/MIP-1β, CCL5/RANTES, CCL17/TARC, CCL18/PARC, CCL22/MDC and CXCL8/IL-8, and their correlation with PsO severity and pruritus intensity." (PMID 36362116, 2022).
renal carcinoma (2 papers, 2020 to 2026). A carcinoma arising from the epithelium of the renal parenchyma or the renal pelvis. "CCL3 is a macrophage chemoattractant that has been shown to promote metastasis in a pre-clinical model of experimental renal cancer metastasis." (PMID 32469992, 2020). "This study aimed to evaluate the usefulness of the C-C motif chemokine ligand 3 (CCL3) and C-C motif chemokine ligand 7 (CCL7) by assessing their serum concentrations in 40 patients with stage G1 + G2 and stage G3 + G4 renal cancer, as well as in 58 healthy volunteers." (PMID 41828706, 2026).
renal fibrosis (2 papers, 2015 to 2016). A final common manifestation of a wide variety of chronic kidney diseases characterized by glomerulosclerosis and tubulointerstitial fibrosis. "Blockade of CCR1, a chemokine receptor for several ligands, including CCL3, 5, 7, 8, 14, 15, 16, and 232, by use of the antagonist BX471, was found to reduce cell accumulation and renal fibrosis in unilateral ureter obstruction." (PMID 26648169, 2015).
respiratory failure (2 papers, 2009 to 2020). The significant impairment of gas exchange within the lungs resulting in hypoxia, hypercarbia, or both, to the extent that organ tissue perfusion is severely compromised. "Interestingly, although neutrophils are recruited to the lung parenchyma in response to CCL3 via coordination by IFNγ, these cytokines alone clearly are not sufficient to induce the inflammatory state that ultimately promotes lung damage and respiratory failure." (PMID 19298652, 2009). "Interestingly, weight loss is sustained among the mice overexpressing CCL3 while receiving supplemental IFNγ over the 9 day examination period, but, despite the substantial inflammatory response, we observe no progression to respiratory failure up to and including t = 14 days." (PMID 19298652, 2009). "Besides expression of pro-inflammatory cytokines, such as IL-1β and TNF-α, the expression of chemokines CCL2, CCL3, CCL20, CXCL1, CXCL3, CXCL10, IL-8 was shown likely to contribute to clinical observation of excessive inflammatory tissue damage, lung injury, and respiratory failure." (PMID 33362782, 2020).
spinal cord injury (2 papers, 2020 to 2021). Penetrating and non-penetrating injuries to the spinal cord resulting from traumatic external forces (e.g., WOUNDS, GUNSHOT; WHIPLASH INJURIES; etc.).
staphylococcus aureus infection (2 papers, 2014 to 2024). An infectious process in which the bacteria Staphylococcus aureus is present. "Differentially expressed genes (DEG) of CCL3+C1QA+ Mp were enriched in terms such as ‘staphylococcus aureus infection’ and ‘antigen processing and presentation’, supporting their role in chemotaxis." (PMID 38601143, 2024).
tuberculosis meningitis (2 papers, 2015 to 2021). "CCL3 is elevated in CSF from patients with posthemorrhagic hydrocephalus and hydrocephalus associated with tuberculous meningitis, which both associate with inflammation." (PMID 34863228, 2021). "Elevated CSF MIP-1α/CCL3 also occurs in bacterial and tuberculosis meningitis, and an increased CSF CCL3/CXCL10 ratio prior to ART initiation is associated with future cryptococcal-IRIS." (PMID 25651842, 2015).
abortion (1 paper, 2017). the ending of pregnancy by removing a fetus or embryo before it can survive outside the uterus. "The same was found for the expression of proinflammatory factor CCL3, which was expressed more (p < 0.01) in samples from animals in which abortion was induced." (PMID 28954628, 2017).
abscesses (1 paper, 2015). "Of the host genes tested, we found that transcripts encoding IL-8, IL1β, oncostatin M-like, CCR1, CXCR1 (IL8RA), CCL4 (MIP-1β) and CCL3 (MIP1α)-like proteins were among the most highly up-regulated transcripts during S. aureus abscess formation." (PMID 25719526, 2015). "Transcripts encoding a number of potent pro-inflammatory cytokines, namely IL-8, macrophage inflammatory protein 1α (MIP-1α or CCL3), and 1β (MIP-1β or CCL4), were highly expressed in abscesses on day 6, which correlates with the maximum size of abscesses." (PMID 25719526, 2015).
aortic atherosclerosis (1 paper, 2018). A atherosclerosis that involves the aorta.
aplastic anemia (1 paper, 2013). Anemia resulting from bone marrow failure (aplastic or hypoplastic bone marrow). "Aplastic anemia was characterized by high Tpo and normal CCL3 levels, whereas MDS patients showed normal Tpo and increased CCL3 levels." (PMID 23430540, 2013).
Arterial stenosis (1 paper, 2022). Narrowing or constriction of the inner surface (lumen) of an artery. "Furthermore, the higher grades of arterial stenosis in the CAD group were associated with higher levels of CCL3 and CCL4 gene expression." (PMID 36381642, 2022).
aspergillosis (1 paper, 2020). Aspergillosis is an infection, growth, or allergic response caused by the Aspergillus fungus. "The chemokines (CCL3, CCL2, and CCL5) followed in this study have been previously shown to be associated with aspergillosis since they are involved in the recruitment of neutrophils, platelets, and monocytes, but the molecules responsible for the chemokine production have not been identified." (PMID 31915215, 2020).
basophilic leukemia (1 paper, 2016). "Moreover, CCL3 synergistically enhanced FcεRI-mediated degranulation and the production of CCL2, which is a chemoattractant for T cells and eosinophils in bone marrow-derived murine mast cells and the rat basophilic leukemia 2H3 cell line." (PMID 27829417, 2016).
behavioral disorders (1 paper, 2022). "Based on these findings, modification of neural circuits by CCL3 may be one of general mechanisms underlying behavioral disorders." (PMID 35906621, 2022).
bile duct cancer (1 paper, 2023). "We further showed that CCL3 promoted the metastasis of intrahepatic bile duct cancer cells by regulating VIRMA/SIRT1 pathway in the orthotopic ICC tumor model." (PMID 36691046, 2023).
biliary atresia (1 paper, 2022). A rare, biliary tract disease characterized by progressive obliterative cholangiopathy of the intra- and extrahepatic bile ducts, occurring in the embryonic/ perinatal period, leading to severe and persistent neonatal jaundice and acholic stool. "It has been suggested that the expression of CCL3 and CCL5 are elevated in a time-dependent manner until seven days, indicating that these two molecules are crucial for the pathogenesis of biliary atresia in mice." (PMID 35204421, 2022).
bone metastasis (1 paper, 2025). Transfer of a neoplasm from its primary site to bones. "Six proteins (CSF-1, CCL4, CCL3, CD83, IL-12, and CD244) and three clinical characteristics (LDH levels, bone metastasis status, and liver metastasis status) were incorporated into the predictive model." (PMID 40404633, 2025).
Bradycardia (1 paper, 2020). A slower than normal heart rate (in adults, slower than 60 beats per minute). "At 120 dpi, bradycardia and increased PR interval were similarly detected in T. cruzi-infected ccl3+/+ and ccl3−/− mice, compared with respective NI control groups." (PMID 32194558, 2020). "ECG alterations as bradycardia and increased PR interval, indicating a delay in the conduction of electric impulse together with an increase in the duration of ventricular action potential, were similarly detected in chronically T. cruzi-infected ccl3+/+ and ccl3−/− mice." (PMID 32194558, 2020).
brain inflammation (1 paper, 2024). "Another study pointed out that the OA2 microglial cell subset promotes age-related brain inflammation by expressing some unique inflammatory signals (such as Lgals3 Cst7 Ccl4 Ccl3 Il1b)." (PMID 39440247, 2024).
Burkitt lymphoma (1 paper, 2021). A rare form of malignant mature B-cell non-Hodgkin lymphoma. "In addition, in vitro and in vivo studies in Burkitt lymphoma cells suggest that CCL3 and CCL4 contribute to the rituximab-induced activation of the innate immunity system." (PMID 36046113, 2021).
Cachexia (1 paper, 2017). Severe weight loss, wasting of muscle, loss of appetite, and general debility related to a chronic disease. "Notably, the cachexia-associated, pro-inflammatory TNF was upregulated 2.9-fold after weight loss, while expression of all interleukins (IL1B, IL6, IL10), as well as CCL3 was much lower than in the lean group." (PMID 27900559, 2017).
Cerebellar atrophy (1 paper, 2022). Cerebellar atrophy is defined as a cerebellum with initially normal structures, in a posterior fossa with normal size, which displays enlarged fissures (interfolial spaces) in comparison to the foliae secondary to loss of tissue. "Pro-inflammatory cytokines, including IL-6, IL-9, IL-12, IL-13, GM-CSF, and macrophage inflammatory proteins-1α (MIP-1α/CCL3), increased in patients with cerebellar atrophy and induced inflammation in the cerebellum." (PMID 35326323, 2022).
cerebral aneurysms (1 paper, 2024). "Currently, research on the role of MIP_1A (also known as CCL3) in the development of cerebral aneurysms is limited." (PMID 38709145, 2024).
cholangiocarcinoma (1 paper, 2025). A carcinoma that arises from the intrahepatic biliary tree (intrahepatic cholangiocarcinoma) or from the junction, or adjacent to the junction, of the right and left hepatic ducts (hilar cholangiocarcinoma). "Secreted CCL3 from hepatocytes, enhances cancer spread by triggering VIRMA and its key downstream target SIRT1, which drives the metastasis of intrahepatic cholangiocarcinoma." (PMID 39941858, 2025).